ASIP (agouti signaling protein)
Diseases named in the same sentence as ASIP in open-access papers (continued):
Sharing a sentence is not in itself a finding about the gene and the disease.
melanism (6 papers, 2012 to 2024). "The presence of a unique single base pair mutation in the Agouti Signaling Protein in melanistic Abert’s squirrels (Sciurus aberti) is very likely the causal genetic basis of melanism in this species." (PMID 38396615, 2024). "Mutations in the coding portions of either MC1R or ASIP have been tied to melanism in lizards, birds, and many different groups of mammals." (PMID 38396615, 2024). "We sequenced the MC1R and ASIP genes for five wild-type and seven melanistic S. aberti individuals to search for melanism-associated mutations." (PMID 38396615, 2024). "Melanism is typically caused by mutations in one of two regulatory genes: the Melanocortin 1 Receptor (MC1R) or the Agouti Signaling Protein (ASIP)." (PMID 38396615, 2024). "This novel mutation is different than the 24 base pair deletion in MC1R previously documented in S. carolinensis and western S. niger and the single base pair mutation in ASIP causing melanism in southeastern S. niger." (PMID 38396615, 2024). "Non-synonymous mutations at the MC1R pigmentation gene are associated with melanism on SA/SC, while ASIP, an antagonistic ligand of MC1R, is associated with melanism on Ugi." (PMID 36318577, 2022). "This association, together with the fact that mutations on the N-terminal portion of ASIP (where this substitution occurs) can disrupt binding and lead to melanism in other taxa, suggest a causal role." (PMID 36318577, 2022). "At the level of individual haplotypes, multiple variants in the pampas cat define a large haplotype block that extends throughout the AsipD fosmid and that contains the ASIP melanism mutation." (PMID 25695801, 2015). "In both the pampas cat and the kodkod, mutations in ASIP were identified that are predicted to cause a loss-of-function, and homozygosity for these mutations was completely associated with melanism." (PMID 25695801, 2015). "We discuss these findings in the context of the evolution of melanism, as well as the relative roles of ASIP and MC1R in the origin of such pigmentation variants." (PMID 23251368, 2012). "A novel single base pair mutation in the ASIP gene, unique to S. aberti, was found to be associated with melanism in the species, indicating that melanism in S. aberti evolved independently from other tree squirrels and thus represents an example of convergent evolution." (PMID 38396615, 2024). "While this novel mutation in ASIP is very likely to cause melanism in S. aberti, further experimental studies could confirm that this point mutation causes protein conformation and/or signaling pathway changes." (PMID 38396615, 2024). "Another possibility is that melanism arose in leopards more than once, e. g. hypothesizing a distinct mutation emerging in Africa, since the known ASIP mutation was reported only based on Asian samples." (PMID 28379961, 2017). "We identify mutations of Agouti signaling protein (ASIP) or the Melanocortin 1 receptor (MC1R) as independent causes of melanism in three closely related South American species: the pampas cat (Leopardus colocolo), the kodkod (Leopardus guigna), and Geoffroy’s cat (Leopardus geoffroyi)." (PMID 25695801, 2015). "Therefore, gain of function in MC1R or loss of function in ASIP induce melanism." (PMID 23251368, 2012). "(Additional, less frequent causes of melanism in some mammals include mutations of beta-defensin 103 [an alternative ligand for MC1R], Attractin [an accessory receptor for ASIP], or Mahogunin [an E3 ubiquitin ligase that acts upstream of the MC1R])." (PMID 25695801, 2015). "The most common causes of melanism mutations are gain-of-function alterations in MC1R, or loss-of-function alterations in ASIP, which encodes Agouti signaling protein, a paracrine signaling molecule that inhibits MC1R signaling." (PMID 25695801, 2015).
melanism (continued). "We have sequenced the coding region of the Agouti Signaling Protein (ASIP) gene in multiple leopard and Asian golden cat individuals, and identified distinct mutations strongly associated with melanism in each of them." (PMID 23251368, 2012). "Consistent with the nature of the mutations, melanism caused by MC1R mutations is dominantly inherited, while melanism caused by ASIP mutations is recessively inherited; however, the inheritance pattern of melanism in pampas, Geoffroy’s cat, and the kodkod is not known." (PMID 25695801, 2015). "For the pampas cat and Geoffroy’s cat, chromosomes bearing melanism mutations (ASIP for pampas cat, MC1R for Geoffroy’s cat) do not cluster together; for the kodkod, there is some clustering of melanistic ASIP chromosomes that may reflect recent population history." (PMID 25695801, 2015). "No other ASIP coding sequence variants were identified in the pampas cat or in the kodkod; four intraspecific variants in MC1R were present in the pampas cat, but none of them exhibited an association with melanism." (PMID 25695801, 2015).
basal cell carcinoma (4 papers, 2012 to 2024). A carcinoma involving the basal cells. "ASIP and TYR pigmentation variants are also associated with cutaneous melanoma and basal cell carcinoma." (PMID 22759494, 2012).
cutaneous melanoma (3 papers, 2012 to 2024). A primary melanoma arising from atypical melanocytes in the skin. "Nevertheless, rs4911442 in the NCAO6/ASIP region and associated with cutaneous melanoma, exhibited a high OR (OR = 1.77, 95% CI 0.90–3.50, P = 5.6 × 10−3) in our study, but did not achieve the significance threshold." (PMID 28781888, 2017).
Hyperinsulinemia (2 papers, 2016 to 2022). An increased concentration of insulin in the blood. "In line with this, the patient showed hyperinsulinemia and her SVF cells differentiated better into adipocytes than SVF cells from controls, indicating additional peripheral obesity-related effects of ubiquitous ASIP expression." (PMID 36536132, 2022).
vitiligo (2 papers, 2021 to 2025). Generalized well circumscribed patches of leukoderma that are generally distributed over symmetric body locations and is due to autoimmune destruction of melanocytes. "Several studies have identified specific ASIP gene SNPs associated with an increased risk of vitiligo." (PMID 40837363, 2025).
albinism (1 paper, 2013). A congenital disorder characterized by partial or complete absence of melanin pigment in the eyes, hair, or skin. "In addition to ASIP, IRF4, KITLG, MC1R, SLC24A4, and TYRP1, we chose 41 additional candidate genes with a potential role in human skin color based on their phenotypes in model organisms, or in humans affected with albinism." (PMID 23555287, 2013).
Hermansky-Pudlak syndrome (1 paper, 2025). Hermansky-Pudlak syndrome (HSP) is a multi-system disorder characterized by oculocutaneous albinism, bleeding diathesis and, in some cases, neutropenia, pulmonary fibrosis, or granulomatous colitis. "Additional pigmentation-related genes, such as ASIP (Agouti-signaling protein) and HPS5 (Hermansky-pudlak syndrome 5), also exhibited missense variants." (PMID 40610894, 2025).
keloid (1 paper, 2025). An irregularly shaped, elevated mark on the skin caused by deposits of excessive amounts of collagen during wound healing. "Two loci (rs140716753 [C20orf187 / LINC02871] and rs1205312 [ASIP]) were only significant in the African and European analyses, respectively, and may represent potential ancestry-specific genetic risk factors for keloids." (PMID 40835838, 2025).
keratinocyte carcinoma (1 paper, 2024). A skin cancer arising from the keratin-producing cells of the epidermis. "Most of these genes are pigmentation-related genes (i.e., SLC45A2, TYR, OCA2, MC1R, and ASIP) and have a biological importance of lighter pigmentation in susceptibility to keratinocyte carcinoma." (PMID 38182794, 2024).
cancer (3 papers, 2019 to 2024). A tumor composed of atypical neoplastic, often pleomorphic cells that invade other tissues. "Eight proteins (A4GALT, ASIP, CTSF, MARE1, PDXK, SEM4A, PLAUR, VARS1) were observed to have evidence of multi-trait colocalization between the index protein, intermediate phenotypes, and the index cancer endpoint, which may serve to elucidate aetiological pathways to cancer risk." (PMID 38684708, 2024).
tumor (2 papers, 2016). "Mice were euthanized on various days upon displaying respiratory distress and lungs were compared for pigmented tumor formation and ASIP expression." (PMID 27028866, 2016). "A second possibility is that ASIP provides a protective function that helps maintain lung function in the presence of a higher tumor load." (PMID 27028866, 2016). "In that report the translation initiation factor eIF-4B was identified among several genes transcriptionally down-regulated in the ASIP-expressing tumor cell cultures." (PMID 27028866, 2016). "The most unanticipated result from our studies was that chronic expression of ASIP within the tumor microenvironment provided a survival advantage to mice bearing both subcutaneous tumors and experimental lung metastases." (PMID 27028866, 2016). "Results obtained on Day 12 from this group of mice support the interpretation that ASIP-expressing tumor cells grow significantly more slowly in mouse lungs." (PMID 27028866, 2016). "The suppression of pigment synthesis was dose dependent as judged by a reduction of pigment that was proportional to the number of the ASIP-positive tumor cells in the implantation mixture." (PMID 27028866, 2016). "These experiments would also tell us if secreted ASIP retained inverse agonist activity against MC1R-driven melanogenesis on neighboring ASIP-null tumor cells." (PMID 27028866, 2016). "The pigmentation of tumors in the lungs from mice implanted with the 4:1 and 1:1 admixtures of GFP-marked B16-F10 and mCherry-marked B16-ASIP cells (B16-ASIP-mChy) was proportional to the relative numbers of ASIP-expressing tumor cells." (PMID 27028866, 2016). "We conclude instead that the tumor load difference was due to a 2-fold slower in vivo growth rate of the ASIP-expressing tumors." (PMID 27028866, 2016). "If the tumor vasculature is similarly responsive to α-MSH agonism then ASIP secreted from tumor cells may counter this influence and decrease tumor blood supply." (PMID 27028866, 2016). "The slower growth of tumors in mice implanted with the 1:1 mixtures of parental and ASIP-expressing tumor cells correlated with a significant (Mantel-Cox, p=0.0007) 37% survival advantage over mice injected with equal numbers of the parental B16-F10 cells alone." (PMID 27028866, 2016). "Notably a similar apparent reduction in total tumor mass in lungs from mice receiving 1:1 mixtures compared to those receiving B16-F10 alone was seen regardless if the mixture contained the oligo-clonal or sub-clonal ASIP(+) tumor cells." (PMID 27028866, 2016). "For example, ASIP may influence survival and in vivo tumor growth by inhibition of MC1R found on the tumor vasculature." (PMID 27028866, 2016).
ASIP also shares sentences with these, for which no sentence is quoted: squamous cell carcinoma (3 papers); Insulin resistance (2); anxiety disorder (1); bacterial infection (1); Basal cell nevus syndrome (1); cataract (1); deafness (1); diabetic kidney disease (1); epidermolysis bullosa (1); Fanconi anaemia (1); Hyperglycemia (1); Infertility (1); ischaemic stroke (1); metabolic disease (1); neurological disorders (1); nevus (1); ocular melanosis (1); oculocutaneous albinism (1); type-II diabetes (1); Werner syndrome (1); xeroderma pigmentosa (1).